VIM (vimentin)
Diseases named in the same sentence as VIM in open-access papers (continued):
Sharing a sentence is not in itself a finding about the gene and the disease.
cancer (continued). "The effects of inhibiting extracellular VIM on carcinoma progression have also been evaluated by injecting mice with anti-VIM antibodies and by immunizing mice against VIM." (PMID 39766058, 2024). "We postulate that combining an anti-cell-surface CK antibody with an anti-cell-surface VIM antibody would be an excellent strategy for detecting CTCs, especially those from hybrid E/M carcinomas." (PMID 39766058, 2024). "This study reveals a new direction for novel drug development targeting the soluble vimentin for efficient cancer treatment." (PMID 36923526, 2023). "Vimentin expression is upregulated in epithelial cells undergoing EMT in malignant tumors, and several studies support the notion that vimentin functions as a positive regulator of EMT." (PMID 37161053, 2023). "We use four different methods to show that vimentin is required for cancer cell invasion across the basement membrane and through the interstitial matrix." (PMID 37161053, 2023). "Alterations in the levels of some proteins in the COS–GA group, such as HSPA9, HIST2H2BF, keratin 18, HINT1, and vimentin, were proposed as anti-cancer mechanisms in this study." (PMID 37371778, 2023). "Of note, many of the studies mentioned in this section were conducted in non-cancer cell types, and the precise role of vimentin in regulating ferroptosis in KRAS-mutant cancer remains to be identified." (PMID 37161053, 2023). "Specifically, the epithelial markers E-cadherin and claudin 1 were downregulated in platelet-treated cancer cells, whereas snail, vimentin, fibrin, and plasminogen activator inhibitor-1 were upregulated." (PMID 37601099, 2023). "VIM and cytoskeletal-dependent cell polarization further enhance the migratory ability of cancer cells during the transition." (PMID 37175467, 2023). "Vimentin+ CAFs are related to tumorigenesis, metastasis, recurrence, drug resistance and poor prognosis in patients of several cancers." (PMID 37143134, 2023). "The prognostic value of vimentin expression in various cancers has been well documented in the literature." (PMID 35896898, 2023). "Taking into consideration that EMT is an important step in the process of cancer invasion and metastasis, we have checked the expression of mesenchymal marker vimentin in Cx43-overexpressed cells keeping HeLa WT cells as a control." (PMID 37815438, 2023). "Flunarizine was also found to upregulateE-cadherin but downregulate the vimentin expression, which subsequentlyinhibited cancer cell migration and invasion." (PMID 37854628, 2023). "Because of the potential contribution of the TME in vimentin-null mice, we set out to ensure that vimentin is sufficient in cancer cells to promote metastasis." (PMID 37161053, 2023). "Vimentin is expressed by leukocytes, but also by cancer cells following epithelial-mesenchymal transition (EMT), which is why it is commonly used as marker for mesenchymal phenotypes in EMT studies." (PMID 37497409, 2023). "Conversely, the vimentin intensity detected in the CECs was highest in the HPAECs and HUVECs and lowest in the altered cell population detected in the cancer patient samples." (PMID 37568766, 2023). "Vimentin is a mesenchymal marker that plays roles in various cancers and is targeted by different lncRNAs in cancers and facilitates EMT." (PMID 37088469, 2023). "Abnormal vimentin expression is found in some types of cancer such as primary epithelial cancer or metastasis." (PMID 38046195, 2023). "Both N-cadherin and vimentin are overproduced in numerous cancers and recognized as prognostic biomarkers in cancero-genesis." (PMID 37242569, 2023). "Cancer cells must form invadopodia, a process that relies on vimentin, to cross the basement membrane." (PMID 37161053, 2023). "Vimentin immunostaining was used as an EMT marker of epithelium-derived cancer cells to visualize connective tissue." (PMID 37047791, 2023).
cancer (continued). "By suppressing β-catenin and E-cadherin protein expression and promoting N-cadherin and vimentin translation SNHG6 not only increases cancer cell proliferation but also promotes EMT of cancer cells." (PMID 37735423, 2023). "The average proportion of vimentin-positive cancer cells was 14.7 ± 2.2% in the group of 35 patients before treatment." (PMID 36834676, 2023). "Various cancer tissue types retained tissue structure and epitope staining after this treatment as shown using a duplex immunohistochemistry staining against Vimentin and pan-Cytokeratin." (PMID 37419873, 2023). "Vimentin is also expressed in circulating endothelial cells, which have been shown to also increase in cancer patients." (PMID 35896898, 2023). "As with the proportion of vimentin-positive cancer cells, the change in mRNA expression was inversely proportional to the pretreatment level of VIM expression (R = −0.56, p = 0.07)." (PMID 36834676, 2023). "Two cancer cell lines differ in an intermediate cytoskeleton: ZR-75 cells have a vimentin cytoskeleton, and BT-20 cells have a cytokeratin cytoskeleton." (PMID 37830577, 2023). "Vimentin was required for the heterotypic cancer cell - CAFs interaction, collective invasion, and lung adenocarcinoma metastasis." (PMID 37006265, 2023). "During this process, the epithelial biomarker E-cadherin is suppressed and the stromal biomarker vimentin is induced within cancer cells." (PMID 36867254, 2023). "IL-6 has also been shown to promote epithelial–mesenchymal transition (EMT) in several cancers through the altered expression of E- and N-cadherin, Vimentin, Snail, Twist, and others." (PMID 38067195, 2023). "Except for its well-known critical roles in cancer metastasis, vimentin is also involved in coordinating cell proliferation and providing the platforms for cells to modulate signaling pathways, such as regulating ERK signaling." (PMID 36631457, 2023). "Vimentin is a marker of epithelial-to-mesenchymal transition (EMT); its expression and functions have been implicated in various types of cancer." (PMID 37717112, 2023). "In the majority of the 5 cancer types, PIK3CD expression was linked favorably with the expression of mesenchymal markers such as VIM (Vimentin), TWIST1, SNAI1 (SNAIL), SNAI2 (SLUG), and CDH2." (PMID 37861728, 2023). "An immunoblot analysis of EpCAM, E-cadherin (known epithelial cell markers), and vimentin (known mesenchymal cell markers) was performed to determine the effect of PYCR2 upon cancer cell phenotype." (PMID 37508547, 2023). "Quite unexpectedly, we also identified Cluster 4 to be enriched for small population of both EpCAMhigh and EpCAMlow cells with CD90/CD44/Vimentin/Ki‐67high molecular profile, resembling proliferative cancer stem‐like (CSC) subpopulation." (PMID 36550781, 2023). "Vimentin is frequently researched as a marker of cancer cell epithelial–mesenchymal transition (EMT)." (PMID 37861934, 2023). "The effectiveness of this approach was assessed by isolating CTCs from prostate (n = 17) and pancreatic (n = 5) cancer patients using EpCAM alone, vimentin alone, and both antibodies together." (PMID 37345161, 2023). "Because under the light microscope, it has been observed that there is a reciprocal migration between cancer cells and spindle cells, and immunohistochemical studies confirmed that spindle cells and giant cell components expressed both keratin and vimentin." (PMID 37724114, 2023). "Cancer aggressiveness-related proteins, such as N-cadherin, Vimentin, Twist, MMP-2, MMP-9, and MMP-13, and the glycolytic enzymes PKM2 and GLUT1 were upregulated in ERL-R cells." (PMID 36611972, 2023). "The expression of the epithelial marker (E-Cadherin) was found to be higher in cancer tissue than in adjacent cancer tissue, while the expression of the mesenchymal marker (vimentin, N-Cadherin) was lower in cancer tissue than in adjacent cancer tissue." (PMID 37841010, 2023).
cancer (continued). "Some of the cytoskeleton proteins such as actin, vimentin, cytokeratins, transgelins are already reported to be involved in LN metastasis in various cancers." (PMID 37142981, 2023). "Upregulation of N-cadherin, vimentin, and snail, along with the downregulation of E-cadherin, promotes cancer development by increasing cell migration and metastasis." (PMID 37033630, 2023). "Vimentin is an intermediate filament essential for cell migration, adhesion and cell division, and is frequently upregulated in cancer or metastatic cells." (PMID 36850002, 2023). "This panel included proteins associated with EMT induction (Vimentin-pSer56, NFκB p100/p52 and IKKε-pSer172) or drug metabolism (CYP1B1), which are also known to induce drug resistance to DTX and PTX in cancer cells." (PMID 37596623, 2023). "The prominent changes characterized by EMT are the downregulation of epithelial markers such as E-cadherin and the upregulation of mesenchymal markers such as Vimentin, which are closely related to cancer cell invasion and metastasis." (PMID 38304037, 2023). "During EMT, cancer cells overexpress mesenchymal-related proteins, such as N-cadherin, vimentin, and matrix metallo-proteases (MMP), which enable them to migrate." (PMID 38132928, 2023). "The appearance of vimentin in the extracellular space occurs during early development, wound healing, inflammation, and some types of cancer." (PMID 37356720, 2023). "Among the six types of intermediate filaments, vimentin is one important regulator of cancer cell migration and stiffness, while keratin and lamin also play important roles." (PMID 37864030, 2023). "This technique enables the characterization and classification of CTCs using epithelial and mesenchymal markers (such as EpCAM, E-cadherin, CK8/18/19, vimentin, and Twist) with high collection efficiency, making it ideal for many types of cancer." (PMID 37841010, 2023). "The findings revealed that normal tissues exhibited higher expression levels of SNAI1, ZEB2, and VIM compared to cancer tissues, and cirrhotic tissues showed higher expression levels than cancerous tissues as well." (PMID 37386390, 2023). "Specifically, they observed that E-cadherin expression decreased and vimentin and transforming growth factor-β expression increased, indicating the possible role of miR-1246 in the Wnt/-βcatenin pathway and its relation to cancer progression and metastasis." (PMID 37569812, 2023). "KT inhibits the expression of both vimentin and β-catenin, suppressing the invasion of cancer cells." (PMID 36674719, 2023). "Due to the identification of EMT as a key process in cancer pathophysiology, the last decade saw an increased interest in modulating vimentin." (PMID 37345897, 2023). "Vimentin (a type III intermediate filament protein expressed in mesenchymal cells) has also been demonstrated as an indicator for pre-metastatic cancer cells undergoing EMT." (PMID 37342379, 2023). "One of the key end-stage markers of EMT is vimentin, which appears to be at the center of signaling pathways that control plasticity and migratory capacity of cancer cells, resistance to therapy, and adaptation to changes in the microenvironment." (PMID 36834676, 2023). "Our results also showed that overexpression of SMARCA4 significantly decreased E-cadherin expression, but upregulated vimentin levels in OSCC cancer cell lines." (PMID 36902184, 2023). "While these results seem counterintuitive, it is important to note that surface expression of intracellular molecules on cancer cells has been reported previously for various proteins, including heat shock chaperones, cytokeratin, Vimentin, etc.." (PMID 37082579, 2023). "At the same time, JFD downregulated N-cadherin, vimentin and β-catenin protein expression in cancer cells." (PMID 38104091, 2023). "We showed that platelet-derived EVs from CRC patients induced TWIST1 and VIM in all the cancer cell lines studied, while platelet-derived EVs from HS did not." (PMID 36672299, 2023).
cancer (continued). "Many of these genes, such as VIM, FOSL2, PTN, GPR3, SIAH2, UPP1, S100A2 are associated with cell migration and epithelial-mesenchymal transition (EMT) in several cancers." (PMID 36850002, 2023). "Previous studies identified these vimentin-dependent mechanisms in cancer cell invasive migration, metastasis, and poor prognosis in patients with lung, breast, head and neck, and bone cancer cells." (PMID 37161053, 2023). "The loss of E-cadherin and the upregulation of Vimentin are important events in EMT and cancer cell migration." (PMID 37104007, 2023). "The occurrence of EMT in cancer cells is indicated by the increased expression of mesenchymal markers: vimentin, n-cadherin, and fibronectin." (PMID 38046195, 2023). "Stabilization of vimentin proteins can play a crucial role in cancer cell adhesion, invasion, and survival, leading to local and distant metastasis." (PMID 37915048, 2023). "Due to its upregulation during tumor growth, vimentin is a promising therapeutic target for treating cancers." (PMID 36675043, 2023). "We found that all the fibroblast clusters showed a high expression of the well-defined panCAF markers including COL1A1, DCN, VIM, FAP, and PDPN4, indicating the identified fibroblasts are likely cancer-associated fibroblasts (CAFs)." (PMID 37612267, 2023). "Cytokeratin increases cellular stiffness and inhibits invasive cancer cell behaviors, whereas vimentin drives metastasis or invasiveness." (PMID 36517670, 2023). "An inverse correlation of postradiation changes in the proportion of vimentin-positive cancer cells with the initial number of these cells before treatment was revealed (R = −0.36, p = 0.03)." (PMID 36834676, 2023). "During the process of EMT, the protein expression of E-cadherin is decreased, while the expression of N-cadherin and Vimentin are increased in cancer cells." (PMID 37781083, 2023). "The major one is represented by cancer cells, assessed by the expression of vimentin and the classical ccRCC-specific marker CAIX." (PMID 37736770, 2023). "Formation and elongation of the invadopodia, a proteolytically active plasma membrane projection that facilitates cancer cell invasion across the basement membrane and migration through the collagen-rich interstitial space, requires vimentin." (PMID 37161053, 2023). "In many cancer types, an increase in vimentin and a decrease in E-cadherin were reported during epithelial-to-mesenchymal transition (EMT)." (PMID 37833976, 2023). "In cancer cells EMT is featured by upregulation of mesenchymal markers such as vimentin (VIM), and downregulation of epithelial markers such as E-cadherin." (PMID 37601651, 2023). "Herein, we examined the effects of CVC on the mRNA and protein levels of CCR2, CCL2, VEGF, NF-κB, c-Myc, IL33, and vimentin, which are involved in the progression of cancer." (PMID 37325423, 2023). "We employed real-time quantitative reverse transcription polymerase chain reaction (qRT‒PCR) to assess the expression levels of three biomarkers, vimentin, KRT16, and KRT18, associated with metastasis and EMT in cancer cells following a 48-h hypoxia treatment." (PMID 37780810, 2023). "Vimentin-stimulated DCs were also shown to have a decreased production of anti-cancer cytokines, IL-6 and IL-12." (PMID 36765706, 2023). "The expression and subcellular localization of vimentin are essential for cell movement, which ultimately leads to cancer recurrence and metastasis via SUMOylation of vimentin." (PMID 37833712, 2023). "It has been observed that the VIM protein and its gene play important roles in controlling migration and invasion in different types of cancer; here, it is highlighted that its location in EVs can be associated with the aggressiveness of cancer." (PMID 37629204, 2023). "Silencing the vimentin protein in cancer cells activates AKT and β-catenin signaling and prevents AMPK-mediated autophagy." (PMID 37371778, 2023).
cancer (continued). "TGF-β released during cancer progression increases the levels of β-catenin and vimentin and promotes tumorigenesis and lung tissue fibrosis by upregulating collagen and YWHAZ expression." (PMID 37888708, 2023). "For example, curcumin reduces the metastatic properties of cancer cells by influencing EMT-related proteins such as vimentin, fibronectin, β-catenin, and E-cadherin as well as genes expressed in cancer stem cells such as Oct4, Nanog, and Sox2." (PMID 37371804, 2023). "Vimentin has been well documented to facilitate cancer invasion and metastasis via modulating EMT and focal adhesion." (PMID 36631457, 2023). "EMT leads to cancer cells losing epithelial markers, such as E-cadherin, α-catenin, and γ-catenin, and gaining mesenchymal markers fibronectin, vimentin, and N-cadherin, leading epithelial cancer cells to become more invasive and gain metastatic capabilities." (PMID 36674719, 2023). "The overexpression and secretion of vimentin by endothelial cells in solid tumors renders this protein an excellent target for therapeutic intervention in cancer therapy." (PMID 37568772, 2023). "Metastasis requires mesenchymal changes in the epithelial cancer cells, which are characterized by higher expression of mesenchymal markers like vimentin (VIM) and a decrease in the epithelial markers like E-cadherin (CDH1)." (PMID 37934721, 2023). "This function was also found in PCa as studies in the field found that the upregulation of vimentin led to increased cancer cell invasiveness; this trend was also observed in our study’s in vitro experiments when BUD31 was knocked down." (PMID 37047027, 2023). "Vimentin and N-cadherin were reported to increase allocation of actin into stress fiber formation and enhance the ability of cancer cells to migrate around." (PMID 36922678, 2023). "As a driver of EMT, ZEB1 downregulates canonical epithelial genes (e.g., E-cadherin, occludin) and upregulates mesenchymal markers (e.g., vimentin, fibronectin) in different types of carcinomas." (PMID 37870961, 2023). "Epithelial cells primarily employ cytokeratin in their cytoskeleton, whereas mesenchymal cells use vimentin, and carcinomas hijack this EMT program, where cytokeratin-positive epithelial cancer cells begin to express vimentin to drive invasion and metastasis." (PMID 36982940, 2023). "For instance, VIM and CD44 are associated with mesenchymal phenotypes and are expressed by both mesothelial and carcinoma cells." (PMID 37691350, 2023). "In all carcinomas, the stromal cells markedly expressed vimentin, with diffuse and intense cytoplasmic staining." (PMID 38071286, 2023). "The expression of important markers of EMT and requisite regulators of mesenchymal cell migration, such as vimentin or fibronectin, is downregulated in esophageal and gastric cancer upon STIM1 and/or Orai1 silencing." (PMID 36612099, 2022). "TAMs can upregulate the expression of EMT markers (E-cadherin, N-cadherin, and vimentin) and promote the migration and invasion of cancer cells with the participation of many regulators." (PMID 36359867, 2022). "In our study, mebendazole inhibits the production of S1P, which inhibits FAK phosphorylation, thereby suppressing the expression of vimentin, which is involved in cancer cell migration." (PMID 36500220, 2022). "Here, we uncover a novel strategy for improving clinical diagnosis by regulating vimentin and cytoskeleton remodeling to modulate the immune response of cancer cells." (PMID 36032170, 2022). "The determination of vimentin was thought to be as a predictive factor of poor prognosis in patients with gastric cancer, but this result is still controversial in other cancers." (PMID 36032170, 2022). "Vimentin was also detected at significantly higher levels in saliva collected from oral precancer and cancer patients compared to normal healthy volunteers." (PMID 35498535, 2022).